TLR3 (toll like receptor 3)
Diseases named in the same sentence as TLR3 in open-access papers (continued):
Sharing a sentence is not in itself a finding about the gene and the disease.
tumor (482 papers, 2006 to 2026). "Although TLR3 is primarily associated with tumor suppression, its overexpression in PCa cells has been linked to increased migration and invasion via EGFR and ERBB2 signaling." (PMID 41601666, 2026). "We also examined the correlation between TLR3 and tumor mutation burden (TMB), immune infiltration, and PD-L1 expression." (PMID 40406122, 2025). "TLR3 agonism increases levels of CD11c + M1 macrophages, which are associated with increased phagocytosis and the consequent pro-inflammatory, anti-tumor immunity." (PMID 39988665, 2025). "By causing tumor regression, the poly (I: C) agonist of TLR3 can change tumor macrophages into tumor suppressor macrophages, which release inflammatory cytokines (M1 macrophages)." (PMID 40727443, 2025). "TLR3 activation leads to tumor suppression, and TLR3 directly causes apoptotic effects in cancer cells." (PMID 40844548, 2025). "In a transplanted murine tumor model, enhanced type I IFN signaling in response to TLR3 stimulation with poly(I:C) reduced the number of tumor-associated macrophages (TAMs) in these tumors as well." (PMID 40098954, 2025). "TLR3 activation in cancer cells can enhance the production of pro-apoptotic proteins and increase the susceptibility of tumor cells to chemotherapeutic agents." (PMID 38792335, 2024). "Across solid tumours from differing tissues, toll-like receptor 3 expression has been found to be associated with both good and poor prognosis in cancer, possibly via pro-apoptotic pathways and resistance to anti-tumour drugs, respectively." (PMID 38290287, 2024). "The RNA origami halted tumour growth or even caused tumour regression by stimulating the innate immune response through the Toll-like receptor 3 (TLR3) pathway." (PMID 37498217, 2023). "One example of TLR-3 stimulation, mainly in Batf3-positive dendritic cells and tumor-associated macrophages (TAMs), has been noted for its induction of caspase-3 mediated apoptotic pathways in Non-Small-Cell Lung Cancer (NSCLC)." (PMID 37974615, 2023). "Replacement of one of the two L412F alleles in tumor cells by a CRISPR-Cas9 Knock-In approach is sufficient to restore TLR3-mediated cell death." (PMID 37414800, 2023). "Tumor specific ligands for TLR3 in the form of damage associated molecular patterns (DAMPs) released from tumor and necrotic cells have also previously been identified." (PMID 37404831, 2023). "TLR3 mediated immune responses by triggering tumor cell growth and survivability and are associated with cancer progression." (PMID 37822929, 2023). "In mice with TLR3 deficiency, the incidence of lung metastasis was significantly reduced, and the survival of tumor-bearing mice was significantly prolonged." (PMID 35719975, 2022). "Regarding neoplastic diseases, TLR3 genetic variants were linked to breast, colorectal and nasopharyngeal cancers, while also serving as prognostic factors in colorectal cancer (CRC) and melanoma malignum (MM)." (PMID 33763088, 2021). "Poly-IC is a synthetic analog of viral double-stranded RNA that activates TLR3-mediated signaling, thereby activating APCs and altering tumor-associated macrophages to adopt an immunologically active phenotype." (PMID 33810617, 2021). "Combined TLR3/7/9 deficiency was reported to induce tumor regression dependent on the activities of CD4+ and CD8+ T cells." (PMID 33633744, 2020). "Here, a new association analysis between OS and TLR3 immunohistochemistry expression on tumor cells has been explored according with NSCLC histology." (PMID 32093313, 2020). "According with tumor stage, we observed that both in stage I and stage II adenocarcinoma, TLR3 was significantly associated with a good prognosis (p = 0.0032; HR = 0.5; n = 370) (p = 0.021; HR = 0.52; n = 136)." (PMID 32093313, 2020). "The poly(I:C) agonist of TLR3 can cause tumor regression, such that tumor macrophages are transformed into tumor suppressor macrophages that produce inflammatory cytokines (M1 macrophages)." (PMID 31240216, 2019).
tumor (continued). "In our cohort of 194 stage I NSCLCs investigated by IHC, we observed that TLR3 protein expression on tumor cells is associated with a good OS." (PMID 31582772, 2019). "Analysis of TLR3 in tumor and immune cells can help in identifying high risk stage I patients for which adjuvant treatment would be beneficial." (PMID 31582772, 2019). "Here we show that TLR3, 7 and 9 deficiencies on host cells, after initial tumour growth, result in complete tumour regression and induction of anti-tumour immunity." (PMID 28300057, 2017). "The B6 mice deficient in TLR-3, 7, or 9, which recognizes double-stranded RNA, single-stranded RNA, and double-stranded DNA, respectively, still maintained an ability to suppress tumor formation of P29mtSAMP1 cybrids." (PMID 24098752, 2013). "Several recent studies suggested that TLR3 activation by its synthetic agonist poly(I:C) directly causes tumor cell apoptosis." (PMID 24155891, 2013). "We have described the proapoptotic activity of TLR3 expressed by various tumor cells, uncovered the association of TLR3 signaling with protein synthesis inhibition in tumor cells." (PMID 18199340, 2008). "As for several other genes, altered expression of TLR3 tended furthermore to be associated with increased tumor stage." (PMID 17280610, 2007). "Leveraging innate signaling, the same backbone combined with the TLR-3 agonist poly(I:C) re-activated NF-κB in tumor cells and tumor-associated macrophages; co-treatment amplified virus-mediated cytotoxicity and promoted M1 polarization beyond that seen with either agent alone." (PMID 41598579, 2026). "Furthermore, TLR3 activation triggers the secretion of damage-associated molecular patterns (DAMPs) into the tumor microenvironment, leading to increased cancer cell migration." (PMID 40647457, 2025). "TLR3 rs3775291 seemed to associate with the risk of tumor recurrence in a recessive model." (PMID 41469691, 2025). "For instance, TLR3 is likely associated with both tumor stimulatory and inhibitory effects." (PMID 39988665, 2025). "This study deciphers a novel molecular mechanism of aseptic inflammation in the prostate epithelium caused by the interaction of TRPM8 RNA with TLR3, which exerts a tumor-suppressive role in the prostate by promoting the safeguarding activity of innate immunity." (PMID 38316991, 2024). "In this context, we and others have demonstrated that the delivery of a TLR3 agonist into the bronchoalveolar space reduces the presence of M2-associated arginase- and IL-10-positive AMs in tumor-bearing lungs, possibly through an IFN-αβ dependent mechanism, as suggested." (PMID 38776331, 2024). "For example, FADD is a risk factor, whereas TLR3 is a protective factor for most tumours." (PMID 36583248, 2023). "It has been demonstrated that treatment with CD40 and TLR3 agonists may transform tumor-associated DC into DC capable of stimulating anti-tumor activation of T-cells." (PMID 37298230, 2023). "We therefore examined whether tumor-specific TLR3 expression was required for the observed anti-tumor effect of poly(I:C) by testing against TLR3 deficient WEHI 164 tumors." (PMID 37467718, 2023). "Therefore, the associations of TLR3 with levels of immune cells infiltration suggested that TLR3 played a vital role in regulating tumor immunology of KIRC, LGG and PAAD." (PMID 36419829, 2022). "We summarize the mechanism and clinical trials associated with the role of TLR3 in tumor behavior." (PMID 33986756, 2021). "However, activation of TLR3 in the Lewis lung cancer cell line 3LL induces M1 polarization of tumor-associated macrophages and can inhibit tumor growth." (PMID 33986756, 2021). "Thus, TLR3 was found to be associated with tumour immune infiltration in KIRC and suggested to play a vital role in immune escape in the KIRC microenvironment." (PMID 34531911, 2021). "TLR3 SNPs were associated with infectious, autoimmune, and neoplastic diseases." (PMID 33763088, 2021).
tumor (continued). "However, the typical TLR3-agonist poly (I:C) was capable of inducing M1-like polarization of tumor-associated macrophages, thereby inhibiting the tumor growth in a subcutaneous transplantation tumor model." (PMID 33392206, 2020). "Overall, we believe that the contradictory effects of the TLR3 pathway activation in tumor tissues could be in part associated with the plasticity of cancer cells." (PMID 33147700, 2020). "Collectively, our data indicate that all these TLR3-mediated mechanisms could contribute to explain the association between TLR3 expression on NSCLC tumor cells and a favorable prognosis." (PMID 32093313, 2020). "Furthermore, another important function of TLR3 signaling is its association with tumor cell growth." (PMID 33147700, 2020). "Additionally, it deciphers the importance of signaling through TLR-3 in effectively skewing “tumor-associated macrophages-M2” to “tumor-protective macrophage subtype-M1” in vitro, as well as in vivo, in the tumor microenvironment of the mice." (PMID 30072995, 2018). "The immunotherapy based on the use of a TLR3 agonist and tumor-derived exosomes carrying associated antigens, which could disrupt tumor immune tolerance and immunosuppressive effects." (PMID 28506269, 2017). "Collectively, our experiments reveal an unexpected capacity of TLR3/7/9-deficient mice to induce protective T-cell-dependent immunity, which is associated with substantial changes in the tumour microenvironment, T-cell activation and tumour regression." (PMID 28300057, 2017). "During the first 7–10 days, tumour growth is virtually identical in WT and Tlr3/7/9-deficient mice." (PMID 28300057, 2017). "Again, all TLR3/7/9-deficient mice and WT mice developed tumours during the initial 1–2 weeks post injection (depending on the cell line used), but only Tlr triple KO mice rejected tumours within 40 days." (PMID 28300057, 2017). "Host RNA associated with necrotic cells and tumor-derived exosomes could potentially activate and up-regulate TLR3." (PMID 28717003, 2017). "Overall, the changes induced by TLR3 stimulation were characteristic of a form of metabolic reprogramming consistently associated with the malignant phenotype and often designated as the tumor Warburg effect." (PMID 27791989, 2016). "Dendritic cells (DCs) mount tumor-associated antigens (TAAs), and the double-stranded RNA adjuvant Poly(I:C) stimulates Toll-like receptor 3 (TLR3) signal in DC, which in turn induces type I interferon (IFN) and interleukin-12 (IL-12), then cross-primes cytotoxic T lymphocytes (CTLs)." (PMID 27619885, 2016). "Given that tumor-expressed TLR3 appears to promote apoptosis in transformed breast epithelia, it is reasonable to speculate that the TLR3 rs10025405 variant (protective among the African-American women in our pilot study) alters TLR3 expression." (PMID 24194738, 2013). "Since RT could promote the release of tumor-associated antigens (TAAs)/neoantigens in vivo, poly(I:C) is also recognized to enhance the ability of antigen uptake by activating TLR3 signaling pathway." (PMID 38671318, 2024). "However, TLR3 may be associated with tumor progression, metastasis, and treatment resistance, resulting in poor prognostic outcomes." (PMID 35664309, 2022). "In addition, it was reported that a significant increase in the therapeutic effect of anti-PD-L1 antibodies was obtained by associating an agonist of Toll-like receptor 3 (TLR3), that activated DC and increased infiltration of immune effector cells within the tumor, or standard chemotherapy." (PMID 33920505, 2021). "We found that TRIM3 overexpression significantly attenuated tumor growth, but TLR3 knockout reversed this effect." (PMID 41545343, 2026). "Our murine studies demonstrated sustained tumor suppression via the TRIM3/TLR3 axis over a 15-day period." (PMID 41545343, 2026). "Bioinformatic analysis of TLR3 expression in the NSCLC cohort revealed its progressive downregulation with advanced tumor stage and N stage." (PMID 41545343, 2026).
tumor (continued). "Overall, the TRIM3/TLR3 axis suppressed NSCLC progression by directly inhibiting tumor cell proliferation and modulating the infiltration levels of immune cells via IFN-β secretion." (PMID 41545343, 2026). "For instance, Ampligen, a formulation of poly(I:C) acting as a TLR3 agonist, has demonstrated tumor growth inhibition in early clinical trials." (PMID 41601666, 2026). "Since aspirin is an HMGB1 inhibitor, and we have shown that TLR3 activation induces TLR2 expression, it is possible that the observed effect of the HMGB1 inhibitor on tumor sphere survival is linked to TLR2 and its inability to be activated with its ligand." (PMID 40647457, 2025). "In cancer, TLR3 exhibits a dichotomous role, with its expression correlating with both good and poor prognoses depending on tumor subtype and microenvironment." (PMID 39988665, 2025). "Another cytokine, IL-27, has also been shown to regulate TLR3 expression in specific contexts, such as human melanomas, where it enhances Poly(I/C)-induced tumor growth inhibition in a partially TRAIL-dependent manner." (PMID 40362489, 2025). "For instance, in NSCLC cell lines, TLR3 not only induces cell death through caspase activation, but also enhances the anti-tumor response through CD103 + DCs antigen presentation." (PMID 39988665, 2025). "We also compared the antitumor effects of SUP3 with other TLR agonists in B16F10 tumor-bearing mice treated with the TLR3 agonist PolyI: C and the TLR9 agonist CpG-ODN." (PMID 41291775, 2025). "These trials aim to exploit the ability of rintatolimod to enhance immune activation and promote a more robust anti-tumor response via TLR3 signaling." (PMID 39988665, 2025). "The σC protein from avian reovirus or UV-inactivated avian reovirus can bind to TLR3 on the surface of CD8+ tumor-infiltrating lymphocytes, activating the TLR3/NF-κB/IFN-γ/TRAIL signaling pathway in immune cells." (PMID 40529304, 2025). "Studies have showed that TLR3 is under-expressed in various cancer tissues, and its activation can convert cancer cells from immune tolerance to anti-tumor immunity, enhancing their anti-tumor activity." (PMID 40406122, 2025). "DNMTis stimulate the production of HERV-derived dsRNA in tumor cells, trigger IFN responses through the MAD5 or TLR3 signaling pathways, induce tumor cell apoptosis, and enhance immune infiltration." (PMID 40722734, 2025). "Accordingly, the tumor-bearing mice inoculated with TLR3 knockout cancer cells rescued with NES-TLR3 survived much longer than that with wild-type TLR3 or NLS-TLR3 rescue." (PMID 40675966, 2025). "Study found overactivation of TLR3 led to prolonged pro-inflammatory responses, promoting formation of tumor microenvironment." (PMID 40535567, 2025). "Upon stimulation by a TLR3 agonist, DCs contribute to tumor cell damage induced by antigen-specific CTLs." (PMID 40029556, 2025). "Specifically, the expressions of CXCL10, ICMA1, IL18, ITGAL, SOCS3, and TLR3 were higher in tumor tissues compared to their corresponding paracancerous tissues." (PMID 40838069, 2025). "As shown by immunofluorescence in tumor spheres, TLR3 expression is stronger after the treatment with poly (I:C) and poly (A:U), as well as the expression of CD133, and TLR3 and CD133 co-localize." (PMID 40647457, 2025). "Nevertheless, the development of safer and more potent analogues has carried the torch in exploring TLR3 agonism as an anti-tumor therapy." (PMID 39988665, 2025). "Consistent with the previous work, TLR3 rescue contributed to a remarkable increase in liver metastasis in tumor-bearing mice, while either c-Myc inhibitor or PRMT5 inhibitor suppressed the metastasis induced by TLR3 rescue." (PMID 40675966, 2025). "With regards to the anti-tumor potential of intracellular TLRs, Poly(I:C) has been reported to stimulate the anti-tumor effect of NK cells by activating the TLR3 signaling pathway." (PMID 41568029, 2025).
tumor (continued). "The RNA origami retarded tumor growth after i.p. injection into mice with metastatic colon cancer, but in vivo evidence of TLR3 activation was unavailable." (PMID 39263835, 2025). "The growing understanding of TLR3 activation in anti-tumor pathways has spurred investigations into the clinical potential of TLR3 agonists as anti-neoplastic agents." (PMID 39988665, 2025). "The TLR3‐specific adjuvant ARNAX, when co‐administered with tumor‐associated antigens (TAAs), potently enhanced tumor‐specific CTL activation in lymphoid organs and promoted their trafficking to tumors." (PMID 40672434, 2025). "We have confirmed here that TLR3 activation, either by poly (I:C) or poly (A:U), induced the expression of all tested DAMPs in adherent cells but also in tumor spheres of Detroit 562 cells." (PMID 40647457, 2025). "TLR3 activation in tumor spheres by poly (A:U) induced ABCG2, a marker of drug resistance, which was reduced by the addition of ASA and MF." (PMID 40647457, 2025). "The TLR3-mediated immune activation by these derivatives is believed to enhance the anti-tumor effects through both direct tumor cell death and the potentiation of immune system activation." (PMID 39988665, 2025). "Cell death can also stimulate type 1 interferon (IFN) secretion by tumor cells via Toll-like receptor 3 (TLR3), which leads to production of the chemokine CXCL10, which has been linked to cancer development and progression." (PMID 41149451, 2025). "While TLR3 can influence tumor progression through inflammation and immune modulation, its function is not limited to malignant diseases." (PMID 39988665, 2025). "In antitumor therapy, TLR3 agonists such as Poly(I:C) and its derivatives inhibit tumor growth by activating the immune system, promote effector T-cell infiltration, and enhance the efficacy of immune checkpoint blockade therapy." (PMID 41568029, 2025). "This is likely due to its limited standalone efficacy without combination therapy and its potential to enhance tumorigenic pathways in TLR3-expressing tumor cells." (PMID 39988665, 2025). "First, we found that age at diagnosis differed among patients carrying genetic variants of TLR3 and IL10, suggesting a role of these pathways in the spontaneous, therapy-independent anti-tumor immune response." (PMID 41469691, 2025). "In previously reported models of surgery-accelerated tumor growth, poly(I:C), a known TLR3 agonist, and CpG-DNA, a known TLR9 agonist, have both demonstrated efficacy." (PMID 41208108, 2025). "TLR3 exerts an inhibitory effect on tumor progression, primarily through the activation of immune responses against cancer cells." (PMID 40675966, 2025). "Most studies have focused on the beneficial role of TLR3 in tumor cells, which can lead to the production of cytotoxic cytokines and interferons that promote caspase-dependent cell apoptosis." (PMID 39981252, 2025). "TLR3 enhances the anti-tumor immune response in LUAD by modulating NF-κB signaling and PD-L1 expression, making it a promising prognostic biomarker and therapeutic target." (PMID 40406122, 2025). "Myeloid DCs can be activated by TLR3 with poly (I: C), which leads to an NK cell response and tumor shrinkage, as observed in a study using mice with melanoma." (PMID 40727443, 2025). "Recent clinical and preclinical advances have explored the use of TLR3 agonists in cancer immunotherapy, attempting to capitalize on their potential to enhance anti-tumor responses." (PMID 39988665, 2025). "Taken together, these results suggest that nuclear TLR3 in cancer cells promotes tumor growth and metastasis." (PMID 40675966, 2025).